MYC (MYC proto-oncogene, bHLH transcription factor)
Diseases named in the same sentence as MYC in open-access papers (continued):
Sharing a sentence is not in itself a finding about the gene and the disease.
meningioma (17 papers, 2009 to 2025). A generally slow growing tumor attached to the dura mater. "It has also been found that the methylation of Werner syndrome protein is associated with invasive meningioma occurrence and development via MYC expression regulation." (PMID 34772393, 2021). "K-M survival analysis revealed that CXCL8 and MYC were associated with prognosis of meningioma patients." (PMID 34772393, 2021). "c-MYC expression is associated with tumor aggressiveness, malignancy, recurrent meningioma, and poor clinical prognosis." (PMID 27007654, 2016). "A recent immunohistochemical survey in GI meningiomas identified a number of SC markers, including OCT4, NANOG, SOX2, KLF4, and c-MYC, on microvessels that led to the suggestion that these vessels may be associated with meningioma initiation." (PMID 31083655, 2019). "Furthermore, NF-κB/IL6, PTGS2, MYC/hsa-miR-574-5p, hsa-miR-26b-5p, hsa-miR-335-5p, and hsa-miR-98-5p, which are involved in the transcription factor-miRNA-mRNA coregulation network, were found to be associated with meningioma." (PMID 32832554, 2020). "The therapeutical effectiveness of targeting the CBX7/USP44/c-MYC/LDHA axis in meningioma patients needs to be further explored." (PMID 37791390, 2024). "Taken together, we demonstrated that CBX7 inhibits LDHA transcription and subsequent glycolysis to protect against meningioma development through the destabilization of c-MYC protein." (PMID 37791390, 2024). "Collectively, these data supported the functional role of the CBX7/c-MYC/LDHA axis during meningioma progression." (PMID 37791390, 2024). "As expected, c-MYC overexpression successfully rescued the decreased LDHA expression in CBX7-restored meningioma cells." (PMID 37791390, 2024). "Although the details regarding the specific E3 ubiquitin ligase that targets c-MYC protein for degradation remain to be further elucidated, the present study indicates a novel function of the CBX7/USP44/c-MYC pathway in meningioma." (PMID 37791390, 2024). "More importantly, the role of the CBX7/USP44/c-MYC/LDHA axis is confirmed in human meningioma tissue samples." (PMID 37791390, 2024). "We found that CBX7 restoration dramatically increased the ubiquitin modification level on c-MYC protein in meningioma cells." (PMID 37791390, 2024). "We also identified USP44 protein in c-MYC-immunoprecipitated mixtures in both meningioma cell lines." (PMID 37791390, 2024). "Altogether, our results shed light on the critical role of CBX7 in meningioma malignancy progression and identify the CBX7/USP44/c-MYC/LDHA axis as a promising therapeutic target against meningioma progression." (PMID 37791390, 2024). "A previous study reported that MYC expression is dysregulated in human meningioma, indicating its potential role in oncogenic processes." (PMID 34772393, 2021). "A previous study has reported that MYC is a hub gene in meningioma, which is consistent with our results." (PMID 32832554, 2020). "A significant difference in the percentages of high grade (II and III) and low grade meningiomas exhibiting a strong level of c-MYC expression was identified (P<0.001)." (PMID 27007654, 2016). "In the present study, 38.3% of meningiomas were c-MYC-positive, with 26.6% having weak and 11.7% strong expression." (PMID 27007654, 2016). "We have investigated the expression of merlin, NDRG2, ERBB2, and c-MYC in patient meningioma specimens using immunohistochemistry (IHC)." (PMID 27007654, 2016). "We determined expression of the proteins merlin, NDRG2, ERBB2, and c-MYC in meningiomas using immunohistochemistry and assessed relationships between protein expression and gender, age, tumor grade, and recurrence or regrowth." (PMID 27007654, 2016).
meningioma (continued). "Ng and Chen reported that 19.6% of 51 meningiomas were c-MYC positive, with 11.8% being grade I, 5.9% grade II, and 1.9% grade III." (PMID 27007654, 2016). "Overexpression of c-MYC has been observed in glioblastomas, medulloblastomas, and atypical and anaplastic meningiomas." (PMID 27007654, 2016). "A significant difference was found between the percentages of high grade (II and III) and low grade meningiomas exhibiting strong c-MYC expression (P<0.001)." (PMID 27007654, 2016). "Moreover, we demonstrated that SLC7A1 regulates multiple signaling pathways involved in tumor proliferation, including E2F targets, G2M checkpoint, and MYC targets, in meningioma." (PMID 41184266, 2025). "Consistently, similar results were obtained from RNA sequencing analysis after knocking down SLC7A1 in meningioma cells, further suggesting the potential oncogenic role of SLC7A1 in meningioma through the regulation of E2F targets, G2M checkpoint, and MYC targets pathways." (PMID 41184266, 2025). "SLC7A1 may facilitate the malignant progression of meningioma through the regulation of E2F targets, G2M checkpoint, and MYC targets pathways via the SLC7A1-FOXM1/E2F4 axis." (PMID 41184266, 2025). "Unexpectedly, c-MYC protein levels were remarkably lower in CBX7-restored meningioma cells than in control cells, while c-Myc mRNA levels in CBX7-restored and control cells were comparable, suggesting that c-MYC protein is post-translationally modified by CBX7 restoration." (PMID 37791390, 2024). "The results showed yellow modules are negatively related to the degree of infiltration of resting mast cells in meningioma tissues, thus, genes such as MYC, CXCL2, CXCL8 and FOSL1 in the module, are inversely associated with the degree of mast cell infiltration." (PMID 34772393, 2021). "MYCN, a member of MYC proto-oncogenes, expression levels may have a positive relationship with disease-free survival in astrocytoma and meningioma." (PMID 32122297, 2020). "Furthermore, we identified a significant association between strong c-MYC expression and grades II and III meningiomas, underscoring the importance of the relationship between c-MYC expression and aggressive tumors." (PMID 27007654, 2016). "Therefore, SLC7A1 may facilitate the malignant progression of meningioma through the regulation of E2F targets, G2M checkpoint, and MYC targets pathways via the SLC7A1-FOXM1/E2F4 axis." (PMID 41184266, 2025). "Moreover, based on the COX univariate and multivariate regression analyses showed CXCL8 and MYC might be prognostic biomarkers for meningioma patients." (PMID 34772393, 2021). "The results showed that USP44 overexpression reduced the levels of CBX7-mediated c-MYC ubiquitination in both IOMM-Lee and CH157 meningioma cells." (PMID 37791390, 2024). "Nonetheless, we unveiled that CBX7 expression level negatively correlates with c-MYC level in meningioma patients and CBX7 can destabilize c-MYC protein in a proteasome-dependent manner." (PMID 37791390, 2024). "Previous studies reported that c-MYC can directly transactivate the transcription of LDHA gene, which was confirmed in meningioma cells in this study." (PMID 37791390, 2024). "AQP1, FRZB, PDGFRL, and PECAM1 were consistently underexpressed in meningioma samples; MEDAG, MYC, PAMR1, PDPN and PERP were consistently overexpressed in nearly every meningioma sample by both measurements." (PMID 29073243, 2017). "In addition, we only correlated the expression patterns of CBX7, c-MYC, LDHA, and Ki-67 in 445 meningioma patient samples with the follow-up outcomes of these patients." (PMID 37791390, 2024). "The ChIP–qPCR data showed that c-MYC bound to the first predicted binding site, −180 bp upstream of the transcription start site, but not the second one in meningioma cells." (PMID 37791390, 2024).
meningioma (continued). "Importantly, c-MYC directly binds to the LDHA promoter to activate its transcription in malignant meningioma cells, while CBX7 restoration forces the degradation of c-MYC protein and then attenuates c-MYC-mediated transactivation of LDHA transcription." (PMID 37791390, 2024). "Then, cycloheximide (CHX) was used to block de novo protein synthesis and the protein levels of c-MYC in meningioma cells with or without CBX7 restoration were measured." (PMID 37791390, 2024). "First, we only used two representative malignant meningioma cell lines, IOMM-Lee without NF2 mutation and CH157 with NF2 mutation, to explore the regulation and roles of the CBX7/USP44/c-MYC/LDHA axis." (PMID 37791390, 2024). "The protein levels of c-MYC in meningioma cells with or without CBX7 restoration were then measured by western blotting." (PMID 37791390, 2024). "Mechanistically, CBX7 restoration destabilizes c-MYC protein by transcriptionally suppressing USP44 expression and then inhibits the c-MYC-dependent transactivation of LDHA transcription, thus inhibiting glycolysis activity and subsequent cell proliferation in meningioma cells." (PMID 37791390, 2024). "Next, we overexpressed c-MYC in meningioma cells with or without CBX7 restoration to determine the functional role of c-MYC in the CBX7/LDHA axis." (PMID 37791390, 2024). "DEGs of MYC and CXCL8, miRNAs of miR-29c-3p and miR-145-5p, as well as pathways such as the TNF signaling pathway, cytokine-cytokine receptor interaction, and IL-17 signaling pathway, probably involved in meningioma development, were obtained." (PMID 34772393, 2021). "Expression of merlin, NDRG2, ERBB2, and c-MYC was not significantly different statistically with relation to gender, age, or meningioma recurrence or regrowth." (PMID 27007654, 2016). "c-MYC expression was present in 26.7% of grade I and 11.6% of grades II and III meningiomas." (PMID 27007654, 2016). "Hence, we speculate that the key genes, including MYC and CXCL8, are involved in meningioma progression via the regulating of different pathways such as the TNF signaling pathway, cytokine-cytokine receptor interaction, and IL-17 signaling pathway." (PMID 34772393, 2021). "Although another primary meningioma cell line, HSMN1, was used in the animal model and similar phenotypes were observed, we cannot exclude the existence of other unknown confounders that might affect the conclusion regarding the regulation of the CBX7/USP44/c-MYC/LDHA axis." (PMID 37791390, 2024). "This hypothesis is reinforced by the fact that this AT/RT component was classified as an AT/RT subtype MYC, which is known to be similar to extracranial forms of rhabdoid tumors (non‐neuronal), and in this case, potentially shares the same cellular origin as MAM and meningiomas." (PMID 38565263, 2024). "Since we did not analyze the transcriptome and chromatin binding patterns of CBX7 or c-MYC in meningioma cells with or without CBX7, we cannot exclude the possibility that c-MYC or CBX7 regulates other pathways to mediate the metabolic switch and inhibit cell proliferation." (PMID 37791390, 2024).
cardiac hypertrophy (16 papers, 2013 to 2025). "The FGF18 and FGF22 genes are known to play a role in heart development and physiological processes while the MYC gene is implicated in angiogenesis, cardiomyogenesis, apoptosis, oxidative stress response and plays a major role in initiating and maintaining cardiac hypertrophy and contractility." (PMID 33788842, 2021). "c-Myc overexpression induced cardiac hypertrophy and increased O-GlcNAc levels; whereas a MYC knockout attenuated pressure overload-induced hypertrophy and decreased O-GlcNAc levels." (PMID 38641064, 2024). "On the basis of the bioinformatics analysis and experimental results, we believed that the TGF-β-MYC-ADAMTS2 axis might be a potential therapeutic target for cardiac hypertrophy and HF." (PMID 37498303, 2023). "Therefore, we speculated that the TGF-β-MYC-ADAMTS2 axis might play a role in the development of cardiac hypertrophy and HF, which needs experimental validation." (PMID 37498303, 2023). "These include MYC and FOS which have been shown to play a key role in cell proliferation and transformation and are also involved in the regulation of cardiac hypertrophy." (PMID 25255322, 2014). "MYC and TRIM24, both predicted to be activated by optoVNS, are important cardiac transcription factors involved in cardiac development and both play important roles in modulation of cardiac hypertrophy." (PMID 38047311, 2024). "Targeting the TGF-β-MYC-ADAMTS2 might be a novel therapy to inhibit CF overactivation and reverse cardiac hypertrophy." (PMID 37498303, 2023).
neuroendocrine tumors (16 papers, 2016 to 2025). "While activated MAPK signaling suppresses neuroendocrine lineage differentiation, concomitant overexpression of MYC or BCL2 accelerates neuroendocrine tumor formation." (PMID 39456595, 2024). "Importantly, MYC‐driven non‐neuroendocrine tumors which are resistant to first‐line therapies show reduced CDKN1A/p21 expression and increased ERCC5/XPG indicating they are primed for response to lurbinectedin–berzosertib combination." (PMID 37491889, 2023). "Aurora kinase inhibition represents another indirect strategy to modulate MYC function, with particular relevance in MYCN-driven and neuroendocrine tumours." (PMID 41561634, 2025). "Together, these findings position AURKA inhibition as a mechanistically distinct yet convergent approach within the broader MYC–DDR therapeutic landscape, particularly relevant to aggressive brain and neuroendocrine tumours characterised by elevated MYC activity and replication stress." (PMID 41561634, 2025).
pancreatic adenocarcinoma (16 papers, 2006 to 2024). "Our data suggest that, similar to pancreatic adenocarcinoma, MYC levels predict triptolide response in MB." (PMID 38885332, 2024). "In pancreatic adenocarcinoma, c-MYC controls the activity of PGC-1α, by binding to its promoter and, hence, inhibiting its transcription." (PMID 32354000, 2020). "Because MYC has been reported to repress anti-tumor immune responses in tumors, including in Kras-driven lung and pancreatic adenocarcinomas, MGA may normally act to limit MYC repression of these genes." (PMID 34236315, 2021). "The c-MYC/PGC-1α ratio influences the metabolic phenotype of pancreatic adenocarcinoma cells." (PMID 32354000, 2020).
astrocytoma (15 papers, 2013 to 2025). "In pediatric midline gliomas and astrocytomas with K27M mutations, MYC/PVT1 also exhibited copy number amplification and patients with this subtype experienced a poorer prognosis." (PMID 38287522, 2024). "This newly identified 19q micro-deletion represents a potential novel mechanism underlying MYC dysregulation in astrocytomas." (PMID 38877600, 2024). "Despite differences in molecular alterations associated with the risk allele, MYC network alteration was shared between both oligodendrogliomas and astrocytomas as one of the most significant." (PMID 27282637, 2016). "Further analyses using single-cell RNA sequencing from a separate dataset of seven IDH-mutant astrocytomas revealed that MYC expression was inversely correlated with the copy number of intervals overlapping the region of interest and the aggregate expression of the genes with copy-number loss." (PMID 38877600, 2024). "In addition to increased immunostaining, authors also demonstrated positive correlation of astrocytoma grade with the number of MYC copies." (PMID 33585252, 2020). "Alterations of CDK6, CDKN2A, CDKN2B, FGFR2, and MYC were more likely to be detected in WHO grade 4 astrocytoma, while variations of chromosome 19q had a higher frequency in WHO grade 2–3 astrocytoma." (PMID 38970209, 2024). "IDH‐mutant astrocytoma grade 4 group exhibited a higher frequency of alternations in FGFR2, CDK6, and MYC." (PMID 38970209, 2024). "Several of these genes, including MYC, EGFR, HIF1A, HGF, APOE, TIMP3, and WNT5A have been identified as being important to development of astrocytoma." (PMID 23737970, 2013). "None of the other six IDH-wt astrocytoma cases were reclassified into new entities because none of them possessed the MYC or PDGFR amplification." (PMID 35626060, 2022). "However, the mechanisms driving MYC overexpression have not been fully elucidated, and there remains a large proportion of astrocytomas that appear to lack any oncogenic alterations in PMN genes." (PMID 38877600, 2024). "Our analyses yielded that 86/236 of astrocytomas exhibited no PMN-alterations, a subset of 21/86 displaying relative MYC overexpression." (PMID 38877600, 2024).
kidney cancer (14 papers, 2014 to 2026). Primary or metastatic malignant neoplasm involving the kidney. "Consistently, HIF2A deletion has been shown to reduce MYC transcription in human pVHL-null kidney cancer cells implanted in mice." (PMID 37998757, 2023). "HIF2A also enhances MYC activity in human pVHL-null kidney cancer cell lines and primary mouse embryo fibroblasts." (PMID 37998757, 2023). "Next, we analysed AR activity by quantifying levels of its target genes IGF1R and MYC in enzalutamide and/or PG-treated kidney cancer cells." (PMID 32847068, 2020). "Importantly, we demonstrate the clinical relevance of MYC-driven CoA-isoprenoid axis in human cancer progression, identify CoA-isoprenoid pathway as a potential therapeutic target in kidney cancer." (PMID 40832336, 2025). "Interestingly, among the top co-upregulated TFs in kidney cancer, we prioritized the MYC proto-oncogene, CCAAT Enhancer Binding Protein Data (CEBPD) and RELA proto-oncogene, NK-kB subunit (RELA)." (PMID 37047552, 2023). "Consistent with our fly data, MYC binds to promoter regions of all four PANK genes in mammals, and its expression inversely correlates with that of PANK4 in human kidney cancer pRCC." (PMID 40832336, 2025). "MXI1, a member of the Mad family proteins known to antagonize c-MYC-dependent transcription, has a potential oncogenic role in RCC, as MXI1 knockdown impaired kidney cancer xenograft formation in nude mice." (PMID 36973268, 2023). "For instance, HIF1A binds to MAX and disrupts MYC/MAX complexes, leading to reduced cyclin D2 expression, induction of p21 (CDKN1A), and G1 phase cell cycle arrest in human pVHL-null kidney cancer cell lines." (PMID 37998757, 2023).